RORC (RAR related orphan receptor C)
Diseases named in the same sentence as RORC in open-access papers (continued):
Sharing a sentence is not in itself a finding about the gene and the disease.
chronic mucocutaneous candidiasis (7 papers, 2015 to 2022). "Adults with genetic mutations impairing RORC or STAT3 function have increased susceptibility to chronic mucocutaneous candidiasis due to diminished Th17 function." (PMID 28360910, 2017). "In humans, rare mutations in the genes encoding IL-17F, IL-17RA, IL-17RC, RORc and Act1 are strongly associated with chronic mucocutaneous candidiasis (CMC)." (PMID 26274976, 2015). "Notably, patients with LOF mutations in IL12RB1 or RORC both are susceptible to chronic mucocutaneous candidiasis (CMC) resulting from infection with the common opportunistic fungal pathogen Candida albicans." (PMID 35896601, 2022).
colitis (7 papers, 2013 to 2025). Inflammation of the colon. "Phenotypic pathway analysis, text mining and time-course qPCR replication highlighted several potential cis-QTL candidate genes in colitis susceptibility, including FcgR1, Ptpn22, RORc, and Vav3." (PMID 23442222, 2013). "Others showed, using the exact same RORC inhibitor, that while IL-17A levels were reduced, the production of IL-22 continued and treatment with the RORC inhibitor abrogated experimental colitis." (PMID 34552583, 2021). "Because RORc-Cre will also delete Npm1 in conventional T cells and γδT cells, we examined the function of various T cell subsets and excluded their contributions to exacerbated colitis in Rorccre/+Npm1flox/flox mice by depleting T cells using a CD3 antibody." (PMID 39103576, 2024). "FOXP3+ CD4+ T cells were increased in numbers but not frequencies, while RORγt+ (also known as RORC+) CD4+ T cells were increased in frequencies and numbers, in colitic mice exposed to PFOS while undergoing colitis." (PMID 34792120, 2021).
asthma (6 papers, 2017 to 2025). "In patients with asthma, overexpression of IL-26 is associated with elevated expression of IL-17A, RAR-related orphan receptor C (RORC), IL-1β, IL-6, and tumor TNF, driven by activation of the IL-20R1/IL-10R2 receptor complex." (PMID 41516201, 2025). "If rs4845604 is shown to be associated with reduced levels of the RORγT transcript, then a RORC inhibitor may be an effective treatment for diseases for which this variant has a protective effect, such as asthma." (PMID 29091937, 2017). "RORC mRNA expression in lung tissue is significantly upregulated in patients with asthma, while IL-17 in the peripheral blood, bronchial lavage fluid, and sputum is significantly increased and positively correlated with airway hyperreactivity." (PMID 39858200, 2025). "One study found that RORC mRNA levels in peripheral blood mononuclear cells of children with asthma during acute attacks were significantly higher than those in the remitted and normal control groups." (PMID 39858200, 2025). "RORC is required for naive CD4+ T cells to differentiate into Th17 lymphocytes; RORC mRNA expression is higher in obesity-related asthma, while methylation of the RORC promoter is lower." (PMID 39858200, 2025). "RORC is involved in asthma pathogenesis via Th17 cells downstream of RORC." (PMID 39858200, 2025). "There are no previous studies associating genetic variants in the IL17RC, RORC and NFKB with asthma, however, it is plausible to believe that variants that may interfere in the regulation of these genes play an important role in asthma." (PMID 31168303, 2019). "The precise role of RORγt in asthma has not been fully clarified, but it has been reported that expression of RORγt or RORc, which encodes RORγt, is increased in the peripheral blood mononuclear cells of asthmatics." (PMID 30541898, 2019). "Specifically, we characterized a regulatory variant in RORC gene associated with multiple allergy traits and asthma related traits which have not been reported previously." (PMID 29091937, 2017). "Mitochondrial reactive oxygen species, glutathione S-transferases, arginase 1 and RORC in immune regulation, the Notch pathway, YPEL4 in cell proliferation, and MARCKS in airway mucus secretion play roles in asthma pathogenesis." (PMID 39858200, 2025).
acromegaly (5 papers, 2013 to 2024). Acromegaly is an acquired disorder related to excessive production of growth hormone (GH) and characterized by progressive somatic disfigurement (mainly involving the face and extremities) and systemic manifestations. "iii) Further analysis of the impact of these genes suggests that attenuated RORC expression in somatotroph adenomas is associated with an increased tumor size and a blunted clinical response following SA treatment." (PMID 23825587, 2013). "Further analysis of the impact of these genes suggests that attenuated RORC expression in somatotroph adenomas is associated with increased tumor size and a blunted clinical response." (PMID 23825587, 2013). "Our in vivo findings in somatotroph adenomas demonstrating a correlation between low RORC mRNA expression and increased tumor size support the biological significance of attenuated RORC expression in somatotroph adenomas." (PMID 23825587, 2013). "The RORC gene consists of two isoforms, γ1 and γ2 (γt); RORγ1, the isoform regulated in the microarray analysis of the somatotroph adenomas, is expressed in many tissues." (PMID 23825587, 2013). "Further studies are needed to elucidate the interaction between EMT progression and RORC expression as well as the mechanism by which SA treatment may adversely affect this interaction and lead to poor clinical responses in patients with acromegaly." (PMID 23825587, 2013). "Our study indicates that attenuated RORC may be involved in the poor clinical response to SA treatment in patients with acromegaly." (PMID 23825587, 2013). "Tumor expression of particular genes was found of prognostic/predictive value in acromegaly patients, These genes include basically CDH1 and SSTR2 but also CDKN1B SNAI2, FLNA, ARRB1, SNAI1 RORC ESRP1, and MKI67." (PMID 39497133, 2024). "RORC and SNAI1 expression offered dual and reciprocal information that may help medical treatment decision making in acromegaly, and await full validation with larger series of cases." (PMID 35203668, 2022). "If RORC plays an active role in the mechanism of response to SRLs, this could open a new path in the treatment of acromegaly to improve SRL response, especially since an agonist of RORC has been used to treat refractory metastatic cancer." (PMID 35203668, 2022).
bladder cancer (5 papers, 2022 to 2025). "For example, the candidate gene RORC was reported to regulate glycolysis and drug resistance in bladder cancer." (PMID 40356904, 2025). "In addition, it was revealed that an elevated amount of RORC, with expression that is considered to be downregulated in bladder cancer, has probably led to the inhibition of cell proliferation and glucose metabolism, by suppressing the binding of STAT3 to the promoter of STAT3-mediated genes." (PMID 36230984, 2022). "Bladder cancer patients who had low expression of retinoic acid-related protein (RORC) by IHC also had increased glycolysis and PPP intermediates compared to those with high RORC expression." (PMID 37779896, 2023). "Finally, RORC impairs STAT3 binding to STAT-3 mediated genes, leading to bladder cancer cells being sensitized to cisplatin." (PMID 36230984, 2022). "Furthermore, RORC, via blocking STAT3, might have sensitized bladder cancer cells’ response to cisplatin." (PMID 36230984, 2022).
leprosy (5 papers, 2013 to 2024). Leprosy is a chronic infectious disease affecting primarily the skin and peripheral nervous system. "For example, in two out of four leprosy biopsies, we observed a population enriched for expression of canonical Th-17 genes including RORC, which encodes the Th-17-lineage-defining transcription factor RORγt." (PMID 33053333, 2020). "Within the leprosy spectrum the more resistant paucibacillary form of tuberculoid leprosy had higher IL-17 associated cytokines IL-21, IL-22 and the transcription factor RORC." (PMID 23936569, 2013). "In summary, it is evident that RORC was associated with IL-17+ cells and phosphorylated STAT3 rather than total STAT3 expression revealed functional differences in leprosy and was in agreement with the activation by SOCS1." (PMID 23936569, 2013). "In conformity with our earlier reports antigen stimulated PBMC of both types of leprosy reactions also showed IL-17 to be present in CD4+CCR6+ cells, along with the signature transcription factor RORC and pSTAT3." (PMID 27035913, 2016).
Obesity (5 papers, 2014 to 2025). Accumulation of substantial excess body fat. "In this study, the relative amount of transcripts of the transcription factors AHR and RORC in PBMCs responsible for Th17 and Th22 differentiation were determined in obesity and T2D patients." (PMID 32849564, 2020). "Theoretically, increased peripheral Th22 and Th17 cells could be promoted both/either/neither by AHR and/or RORC signaling in T2D and/or obesity." (PMID 32849564, 2020).
rheumatoid arthritis (5 papers, 2016 to 2024). A chronic, systemic autoimmune disorder characterized by inflammation in the synovial membranes and articular surfaces. "In rheumatoid arthritis, through detecting regulatory elements at the human RORC locus in the T lymphocytes, the NFAT pathway was found to bind to the RORC locus." (PMID 38609863, 2024). "Expression of the Th17 transcription factor RORC was high in rheumatoid arthritis." (PMID 36966292, 2023). "Additionally, B. longum RAPO significantly inhibited Th17 cells and Th17-related genes—IL-17A, IRF4, RORC, IL-21, and IL-23R—in the PBMCs of rheumatoid arthritis patients." (PMID 34867956, 2021). "In our study, we observed that serum RORc levels were higher in RA patients than in controls reflecting the ongoing inflammatory process in rheumatoid arthritis and it confirms and extends the hypothesis that Th17 enrichment occurs in inflamed joints." (PMID 27043554, 2016).
Candida infections (4 papers, 2016 to 2022). "Recently, homozygous loss-of-function mutations in RORC, which encodes RORγ that is important for the induction of Th17 cells, have been described to cause increased susceptibility to mycobacterial infection and Candida infections." (PMID 26845151, 2016). "However, human patients lacking the IL-17A receptor do not suffer from mycobacterial infections, whereas patients with mutations in RORC lack the Th1* subset able to produce both IFN-γ and IL-17 (patients do not produce IL-17 A and IL-17 F) and suffer from both Mycobacterium and Candida infections." (PMID 29270166, 2017).
lymphedema (4 papers, 2018 to 2023). Excess fluid collection in tissues, causing swelling. "They found that multiple SNPs within the VEGFR2, VEGFR3, and RORC genes were associated with lymphedema (p < 0.05)." (PMID 29670853, 2018). "Meanwhile, studies on genetic predisposition of secondary lymphedema have demonstrated a significant association of VEGFR, RAR-related orphan receptor C (RORC), FOXC2, and interleukin-6 (IL6) genes with secondary lymphedema." (PMID 34733847, 2021).
lymphoma (4 papers, 2013 to 2025). A malignant (clonal) proliferation of B- lymphocytes or T- lymphocytes which involves the lymph nodes, bone marrow and/or extranodal sites. "The nuclear receptor RORC is involved in the regulation of circadian behaviors and clock gene expression, and it has also been implicated in lymphoma formation." (PMID 23825587, 2013). "The translation of this effect to humans is not clear as indicated by the fact that no lymphomas were reported in three kindreds bearing loss-of-function mutations in the RORC gene in children up to the age of 9 years while mice develop thymic lymphomas within 4–5 months of losing Rorc." (PMID 39820614, 2025).
atherosclerosis (3 papers, 2019 to 2022). A disease characterized by the build-up of fatty material and calcium deposition in the arterial wall resulting in partial or complete occlusion of the arterial lumen. "Consistent with thevariation in the T-cell subset ratio, in patients with atherosclerosis, theTh17-cell-related transcription factor RORC showed a markedly higher mRNA level(p < 0.05), conversely, the mRNA expression of the Treg cell-relatedtranscription factor Foxp3 was notably reduced (p < 0.05)." (PMID 39076663, 2022). "In this study, we revealed that RORB, RORC, PER1, CRY1, FTO were in close relationship with atherosclerosis, particularly in atherosclerotic lesions with higher immune infiltration." (PMID 34082770, 2021). "All the available evidence suggests that chronopharmacology-based therapy targeting RORB, RORC, PER1, CRY1, or FTO might constitute another approach for the treatment of atherosclerosis." (PMID 34082770, 2021). "FOXP3 and RORC were consistently diminished in leukocytes in our T1DM patients thus indicating reduced levels of Treg like before, as well as decreased Th17, whose role in atherosclerosis is controversial." (PMID 31299986, 2019).
Autoimmunity (3 papers, 2022 to 2024). The occurrence of an immune reaction against the organism's own cells or tissues. "RORγ T, a specific transcription factor encoded by RORC, plays a major regulatory role in Th17 cell polarization and function and is associated with autoimmunity and inflammation." (PMID 36186454, 2022). "However, under RORc deficiency, the number of Th17 cells decreases, inflammatory cell recruitment and infiltration decrease, and the degree of inflammation and autoimmunity is alleviated." (PMID 35935994, 2022). "RORC, the core genes of the circadian clock, is a critical transcription factor for Th17 polarization and function, and it plays a significant role in autoimmunity and inflammation." (PMID 38302916, 2024).
inflammatory bowel disease (3 papers, 2021 to 2025). A spectrum of small and large bowel inflammatory diseases of unknown etiology. "Furthermore, genome-wide association studies (GWAS) report a significant association between inflammatory bowel disease (IBD) and the RORC regulatory variant rs4845604." (PMID 34673799, 2021). "RAR-related orphan receptor C (RORC) cell surface expression on T-cells increased in inflammatory bowel disease (IBD)." (PMID 40507030, 2025).
nasal polyps (3 papers, 2014 to 2022). "Thus, SEB may contribute to the continued production of RORC+ Tregs; consequently, a higher level of inflammatory cytokines in the presence of pathogenic T cells may contribute to the pathogenesis of nasal polyposis." (PMID 35264183, 2022). "The findings demonstrated that RORC+ Tregs were significantly higher in the nasal polyps, especially in eosinophilic polyps, compared to the control mucosa." (PMID 35264183, 2022). "Furthermore, SEB may be involved in the higher expression of RORC and HIF-1α in Tregs, and maintaining the inflammation in sinonasal mucosa could lead to nasal polyposis' pathogenesis." (PMID 35264183, 2022). "Furthermore, SEB may be involved in the expression of RORC and HIF-1α in Tregs and by maintaining the inflammation in sinonasal mucosa that could have a main role in the pathogenesis of nasal polyposis." (PMID 35264183, 2022). "Thus, to further investigate the phenotype of non-asthmatic Korean nasal polyps, we analyzed the mRNA expression of transcription factors, including T-bet, GATA-3, and RORC in UP tissues from CRS patients." (PMID 25361058, 2014).
thymic lymphomas (3 papers, 2013 to 2025). "RORC exhibits an oscillatory expression pattern in different tissues, and mice deficient in the expression of RORC exhibit a high incidence of thymic lymphomas that metastasize frequently to the liver and spleen." (PMID 23825587, 2013).
colon cancers (2 papers, 2018 to 2024). "Together, these data indicate that expression levels of the MAIT17 signature gene IL17A and a positive MAIT17 regulator RORC positively correlate with prognosis of colon cancers." (PMID 39669566, 2024). "We identified RORγt as an important regulator of MAIT17 versus MAIT1 effector function, and revealed a positive correlation of RORC and IL17 expression with the prognosis of colon cancer." (PMID 39669566, 2024). "In addition, decreased expression of RORC and IL17A correlates with worse prognosis in colon cancers." (PMID 39669566, 2024).
Crohn disease (2 papers, 2022). A gastrointestinal disorder characterized by chronic inflammation involving all layers of the intestinal wall, noncaseating granulomas affecting the intestinal wall and regional lymph nodes, and transmural fibrosis. "The addition of FANA-PGK1 or FANA-ALDOA reduced the frequency of RORC+ cells within CD4 lymphocytes obtained from patients with Crohn’s disease, this decrease trending towards significance." (PMID 36131123, 2022).
lupus (2 papers, 2017 to 2023). "The NRs in the autoimmune/immunodeficiency disease group include PPARG (systemic lupus erythematosus), RORC (immunodeficiency), and RXRA (systemic lupus erythematosus)." (PMID 29065888, 2017). "We identified two transcription factors (STAT1 and LTF) that were positively correlated with T-cell subset infiltration in the lupus tubulointerstitium, and three transcription factors (IRF8, RORC and IKZF2) that were positively associated with T-cell subset infiltration in the glomeruli." (PMID 36829595, 2023).
multiple myeloma (2 papers, 2022 to 2024). "When applied to scRNA-seq datasets of Multiple Myeloma (MM) patients, we identified potential regulations in GRNs of three TFs, RORC, MITF, and FOXD2 in dendritic cells, including many known regulations related to MM pathology." (PMID 39062480, 2024). "DeepIMAGER was applied to scRNA-seq datasets of multiple myeloma (MM) and detected potential GRNs for TFs of RORC, MITF, and FOXD2 in MM dendritic cells." (PMID 39062480, 2024). "In multiple myeloma, studies have suggested that Th17 cells are involved in the pathophysiological process of MM, and RORC overexpression is a sign of the accumulation of Th17 lymphocytes in the bone marrow of multiple myeloma." (PMID 36119497, 2022).
ovarian carcinoma (2 papers, 2024 to 2025). A malignant neoplasm originating from the surface ovarian epithelium. "PS VII suppresses ovarian cancer cell proliferation and glycolysis-induced apoptosis via the RORC/ACK1 pathway, suggesting its potential as a chemotherapy agent." (PMID 41425709, 2025). "In our previous research, we have demonstrated that PS VII can inhibit glycolysis, impede the growth of ovarian cancer cells, and promote apoptosis by targeting the RORC/ACK1 signaling pathway." (PMID 38725854, 2024).
periodontitis (2 papers, 2022 to 2023). An acute or chronic inflammatory process that affects the tissues that surround and support the teeth. "On the contrary, the T cells co-cultured with periodontitis BM-MSCs had significantly increased ratio of Th17 population, profoundly upregulated expression of RORC mRNA and secretion of IL-17." (PMID 37490712, 2023). "Consistent with previous findings, we found that a higher level of STAT3 signaling in BM-MSCs from periodontitis mice can induce more IL-17 production and higher expression levels of RORC in CD4 T cells." (PMID 37490712, 2023). "Compared to healthy individuals, periodontitis patients have a decreased expression level of Treg cell-related gene Foxp3 and increased levels of Th17 cell-related genes RAR-related orphan receptor C (Rorc) and IL-17A." (PMID 35222410, 2022).